ATPSCKMT (ATP synthase c subunit lysine N-methyltransferase)
Description:
Mitochondrial protein-lysine N-methyltransferase that trimethylates ATP synthase subunit C, ATP5MC1 and ATP5MC2. Trimethylation is required for proper incorporation of the C subunit into the ATP synthase complex and mitochondrial respiration. Promotes chronic pain. Involved in persistent inflammatory and neuropathic pain: methyltransferase activity in the mitochondria of sensory neurons promotes chronic pain via a pathway that depends on the production of reactive oxygen species (ROS) and on the engagement of spinal cord microglia.
Synonyms: hFAM173B; FAM173B; JS-2
Tractability: Antibody: UniProt predicts a signal peptide or a membrane-spanning region.
Gene: Protein-coding gene on chromosome 5 (10,225,507 to 10,249,897, reverse strand). Ensembl gene ENSG00000150756.
Subcellular location: Mitochondrion membrane
Subcellular location (Human Protein Atlas): Nucleoplasm; Vesicles
Gene Ontology:
Molecular function: protein binding; protein-lysine N-methyltransferase activity
Biological process: peptidyl-lysine trimethylation; positive regulation of proton-transporting ATP synthase activity, rotational mechanism; positive regulation of sensory perception of pain; regulation of mitochondrial ATP synthesis coupled proton transport
Cellular component: mitochondrial crista; mitochondrial membrane; mitochondrion
Genetic constraint (gnomAD): Loss-of-function variants: 21 observed, 21.05 expected, observed/expected ratio (o/e) 1, 90% interval 0.71 to 1.44. The upper end of that interval is the gene's LOEUF score, 1.44, which puts it in group 5 of 6, group 1 being the genes least tolerant of losing a copy. Missense variants: 264 observed, 273.77 expected, observed/expected ratio (o/e) 0.96, 90% interval 0.87 to 1.07. Synonymous variants: 83 observed, 101.37 expected, observed/expected ratio (o/e) 0.82, 90% interval 0.69 to 0.98.
Homologues: Orthologues: chimpanzee ATPSCKMT (99% identical), dog ATPSCKMT (80% identical), pig ATPSCKMT (79% identical), rabbit ATPSCKMT (78% identical), rat Atpsckmt (75% identical), mouse Atpsckmt (75% identical), guinea pig ATPSCKMT (73% identical), macaque ATPSCKMT (70% identical), tropical clawed frog atpsckmt (62% identical), zebrafish atpsckmt (59% identical), Drosophila melanogaster CG3337 (40% identical), Caenorhabditis elegans Y39A1A.21 (34% identical). Paralogues in human: ANTKMT (37% identical).
Diseases named in the same sentence as ATPSCKMT in open-access papers:
ATPSCKMT is named in the same sentence as 3 diseases in open-access papers, as found by Europe PMC text mining. Sharing a sentence is not in itself a finding about the gene and the disease.
ATPSCKMT shares sentences with these, for which no sentence is quoted: Ataxia (1 paper); cancer (1); prostate adenocarcinoma (1).